ECHS1 (enoyl-CoA hydratase, short chain 1)
Diseases named in the same sentence as ECHS1 in open-access papers (continued):
Sharing a sentence is not in itself a finding about the gene and the disease.
tumor (continued). "Enoyl-CoA hydratase short-chain 1 (ECHS1), which links BCAA metabolism to fatty acid pathways, can sense nutrients and increase tumor resistance to apoptosis by promoting its acetylation." (PMID 40437561, 2025). "(E) Representative IHC images showing the levels of ECHS1, GCDH, YEATS2, H3K27cr, and Twist1 in HNC normal vs. tumor tissue samples (n=8) (Scale bar, 100 μm)." (PMID 40810390, 2025). "However, ECHS1 levels were not substantially linked with age, gender, or tumor size (P > 0.05)." (PMID 38169583, 2024). "However, ECHS1 levels were not substantially linked with age, tumor size, or gender (P > 0.05)." (PMID 38169583, 2024). "Our findings also revealed that ECHS1 down-regulation and ALDH2 up-regulation contribute to reduced TME heterogeneity, decreased inflammation, and inhibited AGS and SNU-1 tumor cells migration and proliferation." (PMID 39328412, 2024). "In this investigation, first, the levels of ECHS1 mRNA expression in stomach adenocarcinoma (STAD) were analyzed via the GEPIA platform, which revealed increased levels in GC tumor tissues than in healthy tissues." (PMID 38169583, 2024). "Additionally, we performed IHC to evaluate the levels of ECHS1, GCDH, YEATS2, H3K27cr, and Twist1 in HNC tumor and their matched normal tissue sections." (PMID 40810390, 2025). "In general, proteins involved in fatty acid β-oxidation such as hydroxysteroid (17-beta) dehydrogenase 10 (HSD17B10), enoyl-CoA hydratase, short chain, 1, mitochondrial (ECHS1), enoyl-CoA delta isomerase 1 (ECI1) were down- regulated in tumour-bearing animals (p-value < 0.001)." (PMID 29258509, 2017). "Studies assessing fatty acid synthase, enoyl-CoA hydratase short-chain 1 (ECHS1), HDL-Receptor SR-BI, the lipid transporter CD36, FA catabolic enzymes or the fatty acid transport protein 4 suggest that these genes regulate ccRCC tumor growth and can predict patient survival." (PMID 40902455, 2025).
metabolic disease (6 papers, 2017 to 2025). A congenital disorder (due to inherited enzyme abnormality) or acquired (due to failure of a metabolically important organ) disorder resulting from an abnormal metabolic process. "With advances in iPSC technology, in vitro cell models have become invaluable for studying ECHS1 mutations and related metabolic disorders." (PMID 40804397, 2025). "ECHS1 deficiency causes dyskinesia in valine metabolic disorders or leads to severe metabolic disorders, such as Leigh-like syndrome." (PMID 38248852, 2024). "Inborn metabolic disorders that compromise ECHS1 activity have been linked to urinary acrylyl-CoA conjugate accumulation in infants with pathology severity increasing following palmitate loading." (PMID 35931118, 2022). "However, despite the close association between ECHS1 mutations and various metabolic disorders and neurological pathologies, there remain significant gaps in our understanding of its pathogenic mechanisms." (PMID 40804397, 2025). "In addition to neurological symptoms, patients with ECHS1 mutations often display notable metabolic abnormalities, with elevated lactate and pyruvate levels in blood and cerebrospinal fluid, suggesting severe mitochondrial dysfunction—a hallmark of metabolic diseases." (PMID 40804397, 2025). "Understanding this mechanism provides critical insights into the pathogenesis of ECHS1-related metabolic diseases and offers a foundation for developing potential therapeutic strategies." (PMID 40804397, 2025).
mitochondrial disease (6 papers, 2015 to 2025). "Computational analysis identifies RTN4IP1 and ECHS1 as key OXPHOS genes linked to mitochondrial diseases in humans." (PMID 40301572, 2025). "ECHS-1 deficiency is a mitochondrial disease with a broad spectrum of disease severity; however, it is often severe." (PMID 37297992, 2023). "This work confirms ECHS1 mutations as a cause of mitochondrial disease, and defines the broad phenotypic spectrum of this new disorder which ranges from fatal neonatal courses to survival into adulthood." (PMID 26000322, 2015). "HIBCH deficiency is a mitochondrial disease that is similar to ECHS1 deficiency." (PMID 36064416, 2022). "In conclusion, the identification of 10 unrelated individuals with ECHS1 mutations allowed us to define the phenotypic spectrum of this new mitochondrial disease entity which can be differentiated clinically and biochemically from other molecular causes of Leigh or Leigh-like syndrome." (PMID 26000322, 2015). "A CRISPR/Cas9-based galactose screening identifies key mitochondrial genes involved in OXPHOS and oxidative metabolism, highlighting RTN4IP1 and ECHS1 as uncharacterized regulators with potential implications for mitochondrial diseases." (PMID 40301572, 2025).
infection (3 papers, 2019 to 2025). The state of being infected such as from the introduction of a foreign agent such as serum, vaccine, antigenic substance or organism. "Furthermore, the increased ratio of pro- to anti-inflammatory cytokines compared with WT mice suggests loss of Echs1 results in imbalanced immune responses which may account for the poorer outcomes following infection." (PMID 41426433, 2025). "To explore the roles of HADH and ECHS1 in AML, we downregulated their expressions in MV4-11 and MOLM13 cells via siRNA infection." (PMID 41573739, 2025). "In contrast, well-nourished infected animals exhibited a down-regulation of ECHS1 and ACAA2, suggesting a diminished rate of FAO and a proliferative profile in response to infection." (PMID 31355153, 2019).
neurological disorder (2 papers, 2021 to 2025). "For example, the precise functional changes caused by ECHS1 mutations across different tissues and cell types remain unclear, particularly regarding their roles in neurological disorders." (PMID 40804397, 2025).
autosomal recessive hereditary disease (1 paper, 2020). "Short-chain enoyl-CoA hydratase(SCEH or ECHS1) deficiency, also known as crotonase deficiency, is a rare autosomal recessive hereditary disease (OMIM 616277)." (PMID 32013919, 2020).
cardiovascular diseases (1 paper, 2018). "Data showed that the relative strength of association between the ECHS1 gene and cardiovascular diseases was -log10(p-value) = 2.03394." (PMID 30541556, 2018).
congenital metabolic disorder (1 paper, 2020). "Short-chain enoyl-CoA hydratase (SCEH or ECHS1) deficiency is a rare congenital metabolic disorder caused by biallelic mutations in the ECHS gene." (PMID 32013919, 2020).
heart disease (1 paper, 2018). "The ECHS1 gene is not only associated with heart disease, it is also associated with drug metabolism." (PMID 30541556, 2018).
ECHS1 also shares sentences with these, for which no sentence is quoted: Obesity (4 papers); clear cell renal cell carcinoma (3); deafness (3); epilepsy (3); optic atrophy (3); type 2 diabetes (3); diabetes (2); liver cancer (2); paroxysmal dystonia (2); prostate carcinoma (2); Alzheimer disease (1); ataxia syndrome (1); atherosclerosis (1); Brain atrophy (1); depression (1); dilated cardiomyopathy (1); Failure to thrive (1); focal segmental glomerulosclerosis (1); glioma (1); heart failure (1); hypoaldosteronism (1); Hypoglycemia (1); Hypoglycemic encephalopathy (1); Krabbe disease (1); leukodystrophy (1); liver dysfunction (1); McArdle disease (1); metabolic acidosis (1); mitochondrial short-chain Enoyl-Coa hydratase 1 deficiency (1); movement disorder (1).
A further 15 diseases each share a sentence with ECHS1 in 1 paper.